INSR (insulin receptor)
Diseases named in the same sentence as INSR in open-access papers (continued):
Sharing a sentence is not in itself a finding about the gene and the disease.
Insulin resistance (continued). "Therefore, reduced Insr expression by hyperinsulinemia may be a key, independent factor of INSR downregulation and insulin resistance." (PMID 34921686, 2022). "In general, maternal stress and exposure to elevated plasma corticosterone levels in different models may program insulin resistance and insulin sensitivity in the offspring which may be attributed to alterations in insulin receptor signaling pathway in peripheral tissues." (PMID 35869151, 2022). "The molecular mechanism of insulin resistance, and thus elevated insulin levels, is downstream of the insulin receptor (IR) in at least muscle, liver, and adipose tissue, and may be the result of the accumulation of ectopic lipids, including ceramides and/or diacylglycerols, in these tissues." (PMID 35244142, 2022). "Based on our findings, that HFCS-MFD consumption induces insulin resistance it would be interesting to explore in subsequent studies the effects of HFCS-MFD on insulin receptor signaling within the limbic system and how such changes may potentially relate to neurobehavioral dysfunction." (PMID 34121997, 2021). "Interestingly, high-fat diet-induced insulin resistance abolished the effects of insulin on striatal dopamine release and reuptake, which could be restored with an insulin receptor sensitizing agent." (PMID 34331964, 2021). "A pathogenetic link between psoriasis and T2DM could be traced primarily in the increase in psoriasis of TNF-α, a pro-inflammatory cytokine which plays an important role in the pathogenesis of insulin resistance, through the reduction of the tyrosine-kinase activity of the insulin receptor." (PMID 33834030, 2021). "Thus, when the functional redox threshold in mitochondria is overcome, mtROS disrupt the interaction between insulin receptor (IR) and insulin receptor substrate (IRS) causing insulin resistance and the impairment of adipogenesis, thermogenesis and adipocyte function." (PMID 33670730, 2021). "Globally, apart from psoriatic disease, TNF-α is known to induce insulin resistance both in vitro and in vivo, by reducing tyrosine kinase activity of the insulin receptor, and endothelial dysfunction, and it may contribute to altered cardiac remodeling after myocardial infarction." (PMID 34829740, 2021). "We postulate that augmented hepatic IDE activity in response to glucose and insulin could serve as a mechanism that preserves hepatocytes from being exposed to high levels of portal insulin, resulting in the downregulation of the insulin receptor and appearance of insulin resistance." (PMID 34572095, 2021). "In this paper, we analyzed whether the severe hepatic insulin resistance of an inducible liver-specific insulin receptor knockout (iLIRKO) might generate vascular insulin resistance and dysfunction, and whether insulin receptor (IR) isoforms gene therapy might revert it." (PMID 34440804, 2021). "Interestingly, miR-96 was upregulated in the liver cells with palmitate exposure or with HFD exposure, targets IRS1 and insulin receptor and may contribute to fatty acid induced hepatic insulin resistance." (PMID 34831343, 2021). "A reduction in insulin receptor expression is consistent with the development of insulin resistance in the face of chronic elevations in circulating insulin resulting from obesity, and with impairments in hippocampal glutamatergic plasticity induced by insulin resistance." (PMID 33514676, 2021). "“Stress-induced insulin resistance may in part be due to phosphorylation-based negative-feedback, which may uncouple the insulin receptor or insulin receptor-associated proteins from its downstream signaling pathways”." (PMID 34068151, 2021). "Similarly, in adipose and liver tissue, disruption of the insulin signaling IRS‐PI3K‐Akt axis leads to severe glucose intolerance and insulin resistance, as described by many INSR, IRS, and Akt knockout studies investigating their effects on proximal insulin signaling and body glucose homeostasis." (PMID 33038072, 2020).
Insulin resistance (continued). "In addition, obesity facilitates the establishment of hyperinsulinemia and insulin resistance, thereby determining an unopposed activation of the insulin receptor (IR) and the insulin-like growth factor receptor (IGF-1R), which are part of the complex insulin/IGF system (IIGFs)." (PMID 33364239, 2020). "An interesting aspect is that the partitioning of insulin receptor isoforms A and B and of hybrid insulin/insulin-like growth factor-1 receptors among cell types may contribute to insulin resistance in some tissues, but the pathophysiological relevance is unknown." (PMID 32819363, 2020). "Thus, the aggravation of insulin resistance in MG-treated rats may be due to interference with insulin receptor signaling." (PMID 32878255, 2020). "However, the effect of insulin could be due to insulin resistance in endothelial cells which decreases eNOS activity, or to modifications on the downstream substrates of the insulin receptor." (PMID 30717220, 2019). "In addition, it has been observed that the pro-inflammatory cytokine TNF may promote insulin resistance by phosphorylation of the insulin receptor." (PMID 31382516, 2019). "Above all, defective insulin receptor phosphorylation is regarded as the main mechanism by which hypomagnesemia contributes to insulin resistance in T2DM patients, and some epidemiological studies have suggested that adequate Mg2+ intake may reduce T2DM incidence." (PMID 31615167, 2019). "Furthermore, the results of this study also provided preliminary evidence that extracellular galectin-3 binds to the insulin receptor directly and attenuates downstream pathways, suggesting galectin-3 to be a novel targetable link between the insulin resistance and T2DM." (PMID 31109008, 2019). "Defects in INSR, an insulin binding receptor with tyrosine kinase activity, could cause insulin resistance, leprechaunism, noninsulin-dependent diabetes mellitus, and familial hyperinsulinemic hypoglycemia." (PMID 30347747, 2018). "There are pieces of evidence that ENPP1, binding to α-subunit of IR (IRα), impairs IR signaling by inhibiting its autophosphorylation, and consequently insulin receptor substrate-1 phosphorylation and glucose transport contributing, thus, to the development of insulin resistance." (PMID 29619007, 2018). "Indeed, at present, strong evidences indicate that miRNAs are deeply involved in the post-transcriptional fine tuning of several insulin signaling components, from insulin receptor (INSR) to transcription factors; of note, some are altered in T2D and in insulin resistance." (PMID 30469501, 2018). "Mutations in the insulin receptor (INSR) gene underlie rare severe INSR-related insulin resistance syndromes (SIR), including insulin resistance type A, Rabson–Mendenhall syndrome and Donohue syndrome (DS), with DS representing the most severe form of insulin resistance." (PMID 29695048, 2018). "However, severe forms of insulin resistance may occur as uncommon syndromes, either congenital or acquired, in patients with impaired INSR signaling or lipodistrophy." (PMID 30034366, 2018). "Because mice deleted the insulin receptor gene in a liver-specific manner have hyperglycemia and whole-body insulin resistance, we hypothesized that insulin-induced phosphorylation of Akt would be highly attenuated in the liver of ArKO mice compared to that in WT mice." (PMID 30211334, 2018). "Moreover, our results indicate that post-receptor defects in insulin signalling may contribute to insulin resistance in DM patients despite the aberrant alternative splicing of INSR gene." (PMID 28915272, 2017). "However, available studies suggest that reduction of INSR function to the ∼25–50% range results in Type A Insulin Resistance (TA-IR), in which patients present with hyperinsulinemia, acanthosis nigricans, polycystic ovarian syndrome (PCOS), hirsuitism, and hyperandrogenism." (PMID 27856697, 2017).
Insulin resistance (continued). "FFA-associated insulin resistance has been reported to be mediated by a molecular mechanism involving GPR40 and insulin receptor substrate-1 serine kinase, which play critical roles in developing insulin resistance and regulating the insulin receptor signaling pathway, respectively." (PMID 29216237, 2017). "As INSR and IRS-1 expression is suppressed at the post-transcriptional level by miR-96 in hepatocytes, this study further examined whether the upregulation of miR-96 causes insulin resistance in hepatocytes." (PMID 28036389, 2016). "Therefore, HUA induced insulin resistance in H9c2 cardiomyocytes was insulin receptor-mediated." (PMID 26836389, 2016). "Importantly, this constitutive UPR depends on insulin signalling, and disturbance of the INSR/P85/XBP1-mediated constitutive UPR in podocytes, for example, in type 1 diabetes (insulin deficiency) or type 2 diabetes (insulin resistance), is mechanistically linked with glomerular disease." (PMID 25754093, 2015). "Polymorphism in insulin receptor substrates (IRS) may also be linked with intolerance of glucose, which raised the possibility that polymorphism in different postreceptors molecules combined and created a state of insulin resistance." (PMID 26273663, 2015). "Insulin resistance is characterized by decreased insulin action on peripheral organs (primarily the liver and the skeletal muscle) and reduced phosphorylation and activation of the insulin receptor (IR), IRSs and components of the phosphatidylinositol 3-kinase/protein kinase B (AKT) pathway." (PMID 25822220, 2015). "Animal (rodent) studies indicate that androgens may produce insulin resistance by direct effects on skeletal muscle and adipose tissue, mediated by alterations in the insulin receptor –glycogen synthesis, by altering adipokine secretion, and by increasing visceral adiposity." (PMID 26015809, 2015). "Furthermore, TBK1 is involved in insulin receptor signaling and might therefore form a link between inflammation and insulin resistance/diabetes." (PMID 25997745, 2015). "Furthermore, strong evidence has demonstrated that besides hyperglycemia, lipotoxicity is another main pathogenesis of type 2 diabetes-induced insulin resistance by increasing the inhibition of serine phosphorylation of the key mediators of insulin receptor signaling." (PMID 24651118, 2014). "One of the premises of targeting NPP1 as treatment for type-2-diabetes-induced insulin resistance is that the inhibition of insulin receptor and NPP1 interactions happens independently of its pyrophosphatase/phosphodiesterase activity, although the exact mechanism is still unknown." (PMID 25368121, 2014). "This study proved clear effect of C/T polymorphism in the exon 17 of the INSR gene on anthropometric and biochemical parameters (PCOS patients with CC genotype) had higher glucose level compared to those with other genotypes; in other words to have insulin resistance." (PMID 25114673, 2014). "Patients with insulin receptor defects also differ biochemically from other types of insulin resistance by displaying elevated adiponectin, IGFBP1, and SHBG, which are all commonly suppressed in common insulin resistance or lipodystrophy-associated severe insulin resistance." (PMID 23766565, 2013). "Since insulin receptor autophosphorylation is ultrasensitive to changes in the activity of antioxidant systems, the compensatory upregulation of antioxidant enzymes under oxidative stress seems to be a key factor contributing to the development of insulin resistance in neurons." (PMID 23730255, 2012). "Therefore, impaired insulin receptor expression and function in skeletal muscle could represent an important factor contributing to ethanol-induced peripheral insulin resistance." (PMID 23016132, 2012).
Insulin resistance (continued). "This has been proposed because patients with diabetes present skeletal muscle weakness that could lead to changes in the sarcolemma as a result of defects in insulin receptor internalization and processing that have been well described in insulin resistance and diabetes." (PMID 22701119, 2012). "Taking that into account, our results underline the important role of insulin receptor-dependent regulation of MMP-9 in macrophages and further extend it to another hyperinsulinemia-related disease state i.e. the development of obesity-associated inflammation and insulin resistance." (PMID 20463885, 2010). "Disruption in vesicle transport affects insulin receptor trafficking and GLUT4 recycling, contributing to peripheral insulin resistance." (PMID 41567335, 2025). "Elevated Zn levels impair insulin receptor phosphorylation and GLUT4 translocation, contributing to insulin resistance and hyperglycemia." (PMID 41459237, 2025). "Key proteins involved in insulin signaling, including the insulin receptor (IR), insulin receptor substrate (IRS), and phosphatidylinositol 3-kinase (PI3K), play critical roles in the development of insulin resistance." (PMID 40004236, 2025). "Insulin resistance also occurs in patients with CC, possibly due to TNF-α, which blocks the phosphorylation of the insulin receptor substrate (IRS), impairing insulin signaling." (PMID 41514616, 2025). "Animal studies highlight Neu-1’s role in obesity, insulin resistance (IRES), and non-alcoholic fatty liver disease (NAFLD) by regulating adipocyte hypertrophy, insulin receptor (IR) signaling, and hepatic lipid metabolism." (PMID 39861189, 2025). "Induction of Insulin Resistance: Oxidative stress disrupts the activation of phosphatidylinositol 3-kinase (PI3K) by impairing the phosphorylation of insulin receptors (InsR) and insulin receptor substrates (IRS)." (PMID 40979172, 2025). "The overexpression of kinase-dead insulin receptor (IR) or IGF-1 receptor (IGF1R) in muscle leads to glucose intolerance, high levels of circulating triglycerides, and insulin resistance in mice." (PMID 40141045, 2025). "TNF-α directly impairs insulin signalling by increasing serine phosphorylation of insulin receptor substrates (IRS), promoting insulin resistance." (PMID 40700071, 2025). "Impaired insulin receptor (IR) signaling and AKT phosphorylation are hallmarks of insulin resistance." (PMID 40332318, 2025). "As shown in the insulin resistance pathway, expression of IL6 and IRS1 were upregulated, while INSR was downregulated in T2DM macaques." (PMID 40878918, 2025). "Inflammatory pathways and oxidative stress—driven by NADPH oxidase activation and proinflammatory cytokines such as TNF‐α and IL‐6—also contribute to insulin resistance by inducing serine phosphorylation of IRS‐1 and impairing insulin receptor activity." (PMID 41143273, 2025). "These kinases phosphorylate insulin receptor substrates (IRS), reducing glucose transporter type 4 (GLUT4) -mediated glucose uptake and contributing to hyperglycemia and systemic insulin resistance." (PMID 41235339, 2025). "These miRNAs influence critical insulin signalling genes (INSR, PIK3R1, AKT2) and steroidogenic regulators (STAR, CYP19A1), hence propagating insulin resistance and steroidogenic dysregulation to adjacent granulosa cells." (PMID 41010046, 2025). "Furthermore, elevated TyG levels are frequently linked to chronic inflammatory responses, characterized by increased concentrations of proinflammatory cytokines such as TNF-α and IL-6, which may further impede insulin receptor signaling and exacerbate insulin resistance." (PMID 40626240, 2025). "InsR is a type 2 receptor tyrosine kinase that could activate the downstream IRS-PI3K-AKT pathway, playing essential roles in regulates glucose metabolism by phosphorylating various downstream proteins, which is closely associated with insulin resistance and diabetes mellitus." (PMID 40507910, 2025).
Insulin resistance (continued). "Il1b is known to disrupt insulin signaling pathways by activating NF-κB and reducing insulin receptor substrate (IRS) phosphorylation, thereby contributing to systemic insulin resistance." (PMID 41019552, 2025). "These pathological changes impair the phosphorylation of insulin receptor (IR) substrates and disrupt the PI3K/AKT signaling pathway, thereby weakening the metabolic effects of insulin and ultimately leading to insulin resistance." (PMID 41267926, 2025). "Mechanistically, ceramide accrual impairs Akt signaling and promotes insulin resistance, while DAG-driven PKC activation diminishes proximal insulin receptor signaling." (PMID 41373990, 2025). "By dephosphorylating tyrosine residues on the insulin receptor, the insulin receptor cannot bind to insulin, thus blocking the activation of the downstream PI3K/Akt signaling pathway and triggering insulin resistance." (PMID 40076586, 2025). "Previous research discovered that impaired insulin receptor signaling contributed to insulin resistance of diabetes mellitus, and BACE1 was identified to regulate the InsR level in HUBC mice." (PMID 40507910, 2025). "Elevated blood concentrations of fatty acids induce inflammatory cytokine release, block insulin receptor signaling through inhibition of insulin receptor substrates (IRS), and provoke insulin resistance." (PMID 41002956, 2025). "Abnormal phosphorylation of IRS-1 results in decreased sensitivity of insulin binding to InsR and a partial translocation of IRS-1 from the membrane to the cytoplasm, which is a major molecular basis for insulin resistance." (PMID 39966707, 2025). "Specifically, 47 targets were observed in GO analysis, observation shows INSR, NF-κB, Akt, GSK-3 and Raf, which regulates insulin signalling and insulin resistance pathway, these pathways contribute in the development of specifically type 2 diabetes." (PMID 40126146, 2025). "The insulin receptor governs TGFβ-induced HSC activation, and CRISPR-induced insulin resistance in human HSCs activates liver fibrotic pathways." (PMID 40985048, 2025). "O‐GlcNAc modification has the potential to impair insulin receptor signaling as insulin receptor substate‐1 (IRS‐1) (Ser1101) and IRS‐2 (Ser1149) become glycosylated following an increase in UDP‐GlcNAc pools, contributing to insulin resistance." (PMID 39279604, 2025). "It contributes to insulin resistance by inducing serine phosphorylation of IRS-1, which disrupts its interaction with the insulin receptor." (PMID 40722699, 2025). "These protein kinases activate the nuclear factor kappaB, promote the transcription of pro-inflammatory genes, and the phosphorylation of serine residues in insulin receptor, IRS and other insulin signaling molecules, implying insulin resistance." (PMID 39337664, 2024). "Sphingolipids and S1P indirectly impact the PI3K/Akt signaling pathway by altering insulin receptor autophosphorylation and insulin receptor substrate (IRS) protein activity, which weakens insulin signaling and contributes to insulin resistance development." (PMID 39777222, 2024). "Inflammatory factors trigger pathways that inhibit insulin receptor (IR) and insulin receptor substrate (IRS) phosphorylation, leading to insulin resistance in the body and brain." (PMID 39897964, 2024). "Overexpression of CREG1 increases phosphorylation of InsR and its downstream effectors Akt and GSK-3beta, improving insulin resistance." (PMID 39639394, 2024). "Targeted knockout or ablation of INSR in the liver results in the inability of insulin to suppress hepatic glucose production (HGP), highlighting the critical role of INSR in hepatic insulin resistance." (PMID 39125938, 2024). "Proinflammatory cytokine production during chronic inflammation in neurodegenerative diseases can induce insulin resistance through IRS serine phosphorylation, which decreases IRS interaction with the insulin receptor." (PMID 39830652, 2024).